DEFB103B (defensin beta 103B)
Description:
Exhibits antimicrobial activity against Gram-positive bacteria S.aureus and S.pyogenes, Gram-negative bacteria P.aeruginosa and E.coli and the yeast C.albicans. Kills multiresistant S.aureus and vancomycin-resistant E.faecium. No significant hemolytic activity was observed.
Synonyms: BD-3; DEFB-3; HBD3; hBD-3; DEFB103; DEFB3; HBP-3; HBP3
Gene: Protein-coding gene on chromosome 8 (7,428,888 to 7,430,348, reverse strand). Ensembl gene ENSG00000177243.
Subcellular location: Secreted
Pathways (Reactome):
Immune System: Beta defensins; Defensins
Gene Ontology:
Molecular function: protein binding; CCR6 chemokine receptor binding; chemoattractant activity
Biological process: antibacterial innate immune response; defense response to bacterium; defense response to Gram-negative bacterium; defense response to Gram-positive bacterium; killing of cells of another organism; cell chemotaxis; defense response; positive chemotaxis
Cellular component: extracellular region; Golgi lumen
Homologues: Orthologues: macaque DEFB103B (100% identical), dog CBD103 (78% identical), mouse Defb14 (69% identical), rat Defb14 (67% identical). Paralogues in human: DEFB103A (100% identical).
Diseases named in the same sentence as DEFB103B in open-access papers:
DEFB103B is named in the same sentence as 3 diseases in open-access papers, as found by Europe PMC text mining. Sharing a sentence is not in itself a finding about the gene and the disease. The quoted sentences say what the papers report.
cancer (1 paper, 2012). A tumor composed of atypical neoplastic, often pleomorphic cells that invade other tissues. "Interestingly, in line with a recent report, half of our T2-STIR + FSHD samples showed overexpression of DEFB103B, which is a DUX4-dependent gene involved in the modulation of both adaptive and innate immune responses, and PRAME family cancer testis antigens." (PMID 22719944, 2012).
infection (1 paper, 2024). The state of being infected such as from the introduction of a foreign agent such as serum, vaccine, antigenic substance or organism. "The GOLGA6L6-, DEFB103B-, OR4F29-, or ERCC6-null cells exhibited significant suppression of intracellular Brucella, especially in long-term infections, which updated our knowledge about the host genes involved in Brucella intracellular survival." (PMID 38376367, 2024).
DEFB103B also shares sentences with these, for which no sentence is quoted: psoriasis (1 paper).